AFP (alpha fetoprotein)
Diseases named in the same sentence as AFP in open-access papers (continued):
Sharing a sentence is not in itself a finding about the gene and the disease.
hepatocellular carcinoma (continued). "Additionally, they noted that their hepatoblastoma, hepatocellular carcinomas, and some epithelioid hemangioendotheliomas were associated with raised serum Alpha Fetoprotein levels (AFP)." (PMID 37575625, 2022). "Serum α-fetoprotein (AFP) is the most classic diagnostic marker in hepatocellular carcinoma (HCC)." (PMID 35787690, 2022). "AFP expression in adults is often associated with hepatoma or teratoma." (PMID 35461226, 2022). "At present, AFP is used as a serum biomarker to assist in the diagnosis or screening of high-risk liver cancer patients, but approximately 30–40% of overall hepatocellular carcinoma patients have very low serum AFP levels (<20 ng/ml), which is called AFP-negative HCC." (PMID 33889548, 2021). "Because of the known limitations of ultrasonography (US) alone, we re-evaluated whether complimentary testing for serum alpha-fetoprotein (AFP) is helpful in surveilling for hepatocellular carcinoma (HCC) in high-risk populations." (PMID 32845895, 2020). "It was demonstrated that AFP-EVs activate an efficient antigen-specific immune response that causes significant retardation of tumor growth and an increase in the overall survival of mice with hepatocellular carcinoma Hepa1–6." (PMID 31680949, 2019). "In hepatocellular carcinoma, 5mC biomarkers derived from ctDNA showed better diagnostic and prognostic values than currently used indicators (such as serum-based alpha-fetoprotein [AFP] and TNM staging)." (PMID 30922396, 2019). "The elastography is an important non-invasive tool for monitoring severe cirrhosis and may help in management of hepatocellular carcinoma with the association of serum alpha fetoprotein, clinical, laboratory and imaging findings." (PMID 29947694, 2018). "Our finding shows that the effect of genetic correction could improve prediction efficiency of AFP levels for primary hepatocellular carcinoma risk in the elderly Chinese population." (PMID 29696820, 2018). "70–95% of hepatocellular cancers are associated with increased AFP level." (PMID 29434637, 2017). "Continuous elevation of AFP levels up to the pathological range in adults has been associated with hepatocellular carcinoma, gastric cancer, hepatic necrosis, hepatic cirrhosis, acute hepatitis, chronic active hepatitis, ataxia telangiectasia, Wiskott–Aldrich syndrome, and pregnancy." (PMID 27121855, 2016). "Alpha-fetoprotein (AFP) expression in adults is often associated with hepatoma or teratoma." (PMID 27725724, 2016). "However, given the association of AFP production with hepatic tumors, such as hepatocellular carcinoma and hepatoblastoma, we have performed liver ultrasonography in infants with high levels of AFP in this study to exclude the presence of these tumors." (PMID 26904545, 2016). "Alpha-fetoprotein (AFP) is a diagnostic marker for hepatocellular carcinoma (HCC)." (PMID 25822740, 2015). "In conclusion, serum MDK may serve as a novel diagnostic tumor marker for the detection of hepatocellular carcinomas, particularly in patients with AFP <20 ng/mL and/or at an early stage." (PMID 25737783, 2015). "Thus, it is known that DCP's diagnostic value as a hepatocellular carcinoma marker is similar to that of AFP." (PMID 24999482, 2014). "Hepatocellular carcinoma is often associated with production of alpha-fetoprotein (AFP)." (PMID 23130020, 2012). "The high level of AAG in HCC patients with low AFP concentration could be caused by the inflammation of the liver or the overproduction of the acute phase protein by hepatoma cells." (PMID 21092242, 2010). "Alpha-fetoprotein (AFP) is a well-known diagnostic biomarker used in medicine to detect fetal developmental anomalies such as neural tube defects or Down’s syndrome, or to follow up the development of tumors such as hepatocellular carcinomas." (PMID 19690639, 2007). "Elevated serum levels of alpha-fetoprotein (AFP) are typically associated with hepatocellular carcinoma (HCC) or germ cell tumors." (PMID 40406259, 2025).
hepatocellular carcinoma (continued). "Often used in conjunction with imaging, alpha-fetoprotein (AFP) remains the most widely used biomarker for hepatocellular carcinoma (HCC), but its diagnostic, prognostic, and surveillance capabilities are limited." (PMID 40563578, 2025). "Hepatocellular carcinoma (HCC) remains a leading cause of cancer mortality, and current biomarkers such as alpha-fetoprotein (AFP) lack diagnostic accuracy." (PMID 41474787, 2025). "utilized VirScan to detect a viral exposure signal that was associated with hepatocellular carcinoma and used it prospectively in at-risk patients to identify patients who were going to develop cancer, and their viral exposure signal biomarker was superior to that of the alpha-fetoprotein test." (PMID 39168282, 2024). "The study about serum α-fetoprotein to predict the prognosis of bevacizumab plus immunotherapy in hepatocellular carcinoma have found that the reduction of serum AFP level after anti-PD-1 treatment is associated with a good prognosis for advanced HCC." (PMID 39555053, 2024). "In addition, DKK1 has a more significant diagnostic value than AFP in hepatocellular carcinoma." (PMID 37017469, 2023). "Researchers have studied the accuracy of a new diagnostic panel for hepatocellular carcinoma (HCC), which was identified using miR-122, miR-16 and AFP." (PMID 37998561, 2023). "Regular hepatocellular carcinoma (HCC) surveillance by ultrasonography in combination with the α-fetoprotein (AFP) examination is unsatisfactory in diagnostic sensitivity for early-stage HCC especially in cirrhotic patients." (PMID 35388082, 2022). "For instance, α-fetoprotein (AFP) is an FDA-approved biomarker for hepatocellular carcinoma (HCC), but it is also associated with other benign liver diseases." (PMID 35798744, 2022). "At present, the diagnostic ability of hepatocellular carcinoma (HCC) based on serum alpha-fetoprotein level is limited." (PMID 35739471, 2022). "In clinical studies, tumor markers (such as α-fetoprotein (AFP)), imaging, and histopathological biopsies are commonly used diagnostic tools for hepatocellular carcinoma (HCC)." (PMID 36138197, 2022). "Alpha fetoprotein (AFP) is reactivated in a majority of hepatocellular carcinoma (HCC) and associated with poor patient outcomes." (PMID 33009373, 2020). "The administration of a single dose of DEN in mice led to the formation of hepatocellular carcinoma, causing significant damage to the lungs, kidney and testis, with the animals presenting with altered liver function parameters and elevation of the tumor marker alpha fetoprotein." (PMID 31141523, 2019). "Increased serum alpha-fetoprotein (AFP) levels are associated withspecific molecular sub-classes of hepatocellular carcinoma (HCC), supportingAFP as a predictive or therapeutic biomarker for precision treatment of thisdisease." (PMID 29376136, 2018). "Therefore, risk factors for the development of hepatocellular carcinoma in these patients were the presence of hepatitis C virus, the serum AFP with cutoff point higher than 9.1 ng/dl and ​​elastography values greater than 9kPa in FibroScan and higher than 2.56 m/s in ARFI." (PMID 29947694, 2018). "Numerous studies have considered AFP as a diagnostic tumor-specific marker for hepatocellular carcinoma (HCC), which has become the fifth most common human cancer with high mortality, in at-risk patients with a cut-off level of 20 ng/mL." (PMID 28353669, 2017). "Here we conducted a retrospective study to evaluate the diagnostic and prognostic value of serum AFP among hepatocellular carcinoma (HCC) patients with their pathogenic features taken into consideration." (PMID 26784252, 2016). "Serum alpha-fetoprotein (AFP) has long been used as a diagnostic marker for hepatocellular carcinoma (HCC), albeit controversially." (PMID 25310463, 2014).
hepatocellular carcinoma (continued). "For hepatocellular carcinoma (HCC), the common method of screening high risk patients by alpha-fetoprotein (AFP) and ultrasonography has been shown to result in earlier detection and consequently more easily treatable tumors and longer survival." (PMID 17407558, 2007). "In hepatocellular carcinoma, which is known to have a high frequency of AFP-producing cancers, only about 40% of the serum AFP positives were also positive for immunostaining." (PMID 41589237, 2026). "Alpha-fetoprotein (AFP) is widely utilized for auxiliary diagnosis of primary hepatocellular carcinoma." (PMID 42042729, 2026). "The real-world risk score for hepatocellular carcinoma (RWS-HCC), developed in Singapore in 2020, incorporates age, sex, cirrhosis, diabetes, platelet count, and alpha-fetoprotein (AFP), all of which are routinely available clinical variables." (PMID 41514666, 2026). "Pathologically, hepatoid adenocarcinoma resembles hepatocellular carcinoma and is characterized by eosinophilic cytoplasm, solid sheet‐like growth, and AFP positivity." (PMID 41190289, 2026). "NTBC concentrations showed limited correlation with alpha‐fetoprotein, reinforcing the continued need for imaging in hepatocellular carcinoma surveillance." (PMID 41510183, 2026). "Hepatocellular carcinoma (HCC) is a leading cause of cancer-related mortality worldwide, yet current surveillance with alpha-fetoprotein (AFP) and ultrasound (US) lacks sufficient accuracy, particularly for early-stage disease." (PMID 42009371, 2026). "Background/Objectives: Hepatocellular carcinoma (HCC) remains a major cause of cancer-related mortality, with diagnostic limitations of existing biomarkers such as alpha-fetoprotein (AFP)." (PMID 40506936, 2025). "Alpha-fetoprotein (AFP) together with Lens culinaris-agglutinin-reactive fraction of AFP (AFP-L3) serve as the preferred tumor markers for hepatocellular carcinoma (HCC) diagnosis." (PMID 40258775, 2025). "At this time Labs investigations were done showing normal levels of liver and renal functions but with a high level of Alpha-photo protein (AFP) which suggests a high incidence of hepatocellular carcinoma." (PMID 40264205, 2025). "Characterized by histological features resembling hepatocellular carcinoma, HAS is frequently associated with elevated serum AFP levels." (PMID 40655149, 2025). "For example, alpha-fetoprotein (AFP) and carcinoembryonic antigen (CEA) serve as diagnostic biomarkers for hepatocellular carcinoma, and colorectal cancer, respectively." (PMID 40949873, 2025). "In the 1980s, with the wide application of radioimmunoassay, it was found that serum AFP was significantly elevated in some patients with malignant tumors other than hepatocellular carcinoma and yolk cystic tumor, such as HAC." (PMID 40740864, 2025). "AFP levels increase not only in hepatocellular carcinoma but also in response to inflammation and fibrosis." (PMID 40870838, 2025). "While AFP is widely recognized as a tumor marker for hepatocellular carcinoma and germ cell tumors, emerging evidence suggests its relevance in gastric cancer, particularly in a rare subtype known as AFP-producing gastric cancer (AFPGC)." (PMID 40299527, 2025). "Alpha-fetoprotein (AFP) is an important biomarker for detecting primary liver carcinoma and for postoperative assessment." (PMID 40278477, 2025). "In summary, these findings indicate that AFP significantly affects macrophage behavior, promoting a pro-tumorigenic environment by inhibiting their phagocytic activity against hepatoma cells." (PMID 40430002, 2025). "Alpha-fetoprotein is a tumor marker expressed by AFP gene and is considered the gold standard tumor marker for hepatocellular carcinoma (HCC)." (PMID 40579398, 2025). "HAS is characterized by both adenocarcinoma and hepatocellular carcinoma like differentiation, which often produces alpha-fetoprotein (AFP) and responds poorly to systemic chemotherapy." (PMID 40235542, 2025).
hepatocellular carcinoma (continued). "In cancer diagnostics, alpha-fetoprotein (AFP) serves as an important serum biomarker for hepatocellular carcinoma, with significant clinical value." (PMID 41440280, 2025). "Approximately one-third of hepatocellular carcinoma (HCC) patients exhibit serum alpha-fetal protein (AFP) negativity, which is very common in cirrhotic patients (Ma, Wang & Teng, 2013), with small liver tumors being particularly prevalent in this group." (PMID 40161339, 2025). "Serum alpha-fetoprotein (AFP) is widely used for hepatocellular carcinoma (HCC) management, yet its limited sensitivity and specificity restrict diagnostic and prognostic utility." (PMID 41002319, 2025). "Pathological examination revealed moderate to high expression of AFP and Ki-67 in all three groups, indicating the formation of hepatocellular carcinoma (HCC)." (PMID 39744233, 2025). "Abdominal Doppler ultrasound or elastography will be scheduled every 6–12 months, while alpha-fetoprotein (AFP) measurement and liver ultrasound every 6 months will be implemented for hepatocellular carcinoma surveillance." (PMID 41169469, 2025). "AFP is mainly known as a marker for hepatocellular carcinoma, but it can be elevated in germ cell tumors, viral hepatitis, liver fibrosis, and neurodegenerative diseases such as A-T." (PMID 40597142, 2025). "A mouse DC cell line was infected with a lentivirus encoding the AFP gene to employ the fetal liver protein-fetoprotein (AFP) as a hepatocellular cancer antigen." (PMID 40234973, 2025). "Atezolizumab plus bevacizumab and lenvatinib are standard treatments for unresectable hepatocellular carcinoma; however, tumor markers such as alpha-fetoprotein and des-gamma-carboxy prothrombin have a limited ability to reflect treatment responses." (PMID 40940925, 2025). "Lipocalin-2 (LCN-2) has demonstrated superior diagnostic performance for hepatocellular carcinoma (HCC), surpassing traditional biomarkers such as alpha-fetoprotein (AFP)." (PMID 40625923, 2025). "The baseline AFP level is an independent predictor of the prognosis of patients with advanced hepatocellular carcinoma." (PMID 40221793, 2025). "Among neoplasms that involve an increase in the production of AFP, there are hepatocellular carcinoma and cancers involving the stomach, pancreas, biliary tract, and lungs, in which AFP can be used as a tumor marker to support their diagnosis." (PMID 40723290, 2025). "Increased levels of ALT, AST, and AFP were found, reflecting liver damage and advancement towards hepatic carcinoma." (PMID 40922741, 2025). "Alpha-fetoprotein (AFP) as a more sensitive and specific biochemical marker of primary hepatic carcinoma (PHC)." (PMID 39991578, 2025). "The presence of AFP production and genetic abnormalities reiterates the importance of accurate differentiation from hepatocellular carcinoma and intrahepatic cholangiocarcinoma, as their treatment approaches and prognoses differ." (PMID 39522069, 2025). "Accurate and early detection of alpha-fetoprotein (AFP) in human serum is essential for the diagnosis and monitoring of hepatocellular carcinoma and related diseases." (PMID 41294739, 2025). "Alpha-fetoprotein, identified more than 60 years ago, is the most used biomarker for the screening, diagnosis, prognostication, and assessment of treatment for hepatocellular carcinoma." (PMID 40426850, 2025). "ICT induces antitumor immune responses in hepatocellular carcinoma by downregulating alpha fetoprotein gene expression and exacerbating mitophagy and synergizes with doxorubicin to induce immunogenic cell death in hepatocellular carcinoma." (PMID 41019997, 2025). "Prior to the omics era, numerous biomarkers had already been successfully implemented in clinical practice, such as HER2 for breast cancer and AFP for hepatocellular carcinoma." (PMID 41269529, 2025).
hepatocellular carcinoma (continued). "HAC morphologically resembles hepatocellular carcinoma, is characterized by alpha-fetoprotein (AFP) production, and exhibits aggressive behavior with resistance to conventional chemotherapy, early liver metastasis, and poor prognosis." (PMID 41346621, 2025). "Hepatocellular Carcinoma Early Detection Screening (HES) is a screening technique that combines AFP with age alanine aminotransferase and platelets." (PMID 40269686, 2025). "Many other protein markers, such as alpha-fetoprotein (AFP), a biomarker of hepatocellular carcinoma (HCC), rely on the changes in their protein glycosylation in the detection of cancer." (PMID 40890283, 2025). "Histologically, HAS resembles hepatocellular carcinoma, characterized by abundant eosinophilic cytoplasm, centrally located nuclei, and frequent elevation of serum alpha-fetoprotein (AFP)." (PMID 40655149, 2025). "For example, prostate cancer diagnosis frequently relies on prostate-specific antigen (PSA) levels, and hepatocellular carcinoma (HCC) often employs alpha-fetoprotein (AFP) screening." (PMID 40001982, 2025). "Overexpression of X protein of hepatitis B virus resulted in the significant decrement of miR-1236-3p and increment of alpha-fetoprotein (AFP) in the hepatoma cells." (PMID 40502714, 2025). "A recent phase 3 biomarker study prospectively compared the performance of GALAD scoring and alpha-fetoprotein (AFP) in early detection of hepatocellular carcinoma (HCC)." (PMID 41471145, 2025). "•Alpha-Fetoprotein (AFP): AFP serves as a biomarker for detecting liver tumors (e.g., hepatocellular carcinoma) and germ cell tumors." (PMID 40125297, 2025). "In conclusion, ultrasonography combined with AFP, SAA, and CRP significantly improves early detection of hepatocellular carcinoma in high-risk populations." (PMID 40660552, 2025). "The final variables included via LASSO included HBsAg and AFP, both of which are clinically specific markers for liver injury and are widely used in hepatocellular carcinoma surveillance." (PMID 40790537, 2025). "In recent years, alpha-fetoprotein (AFP) has garnered significant attention and has emerged as the most widely utilized protein biomarker for diagnosing hepatocellular carcinoma (HCC)." (PMID 39942588, 2025). "Patients with hepatocellular carcinoma also had response assessed by trends in alpha‐fetoprotein level." (PMID 38629258, 2024). "Subsequent studies have elucidated that AFP can impede the phagocytic activity of macrophages toward hepatoma cells and other tumor cells through its interaction with macrophage receptors." (PMID 38660138, 2024). "AFP is the most common biomarker of hepatocellular carcinoma (HCC) in blood samples, and has been considered as such since its discovery and assessment about 60 years ago." (PMID 38396756, 2024). "Kim and co-workers evaluated AFP and radiographic changes in 108 patients with hepatocellular carcinoma and concluded that AFP changes provide prognostic information after management with immune checkpoint inhibitors." (PMID 38671768, 2024). "Traditional CAR-T cell therapy for hepatocellular carcinoma cause serious side effects, including cytokine release syndrome (CRS), and the AFP peptide-MHC complex is less expressed on the surface of tumor cells." (PMID 39136031, 2024). "Given his previous burden of hepatitis B infection, and the serum AFP level on admission was high (212.6 ng/mL), this raised suspicions of possible hepatocellular carcinoma." (PMID 38449931, 2024). "Serum AFP is a widely used hepatocellular carcinoma (HCC) biomarker and, in the Afphi branch 1, we identified an intermediate cellular state, largely corresponding to the Dlk1+/Gpc3+ ‘hepatoblastic cluster’ (bottom)." (PMID 39112713, 2024). "Among hepatocellular carcinoma, ephrinA1 also stands out as a significant biomarker, correlating with increased levels of alpha-fetoprotein and being involved in tumor growth and metastasis." (PMID 39839790, 2024).